MTOR (mechanistic target of rapamycin kinase)
Diseases named in the same sentence as MTOR in open-access papers (continued):
Sharing a sentence is not in itself a finding about the gene and the disease.
thyroid cancer (continued). "The PI3K/Akt/mTOR pathway is primarily activated at different targets in diseases with BRAF and RAS mutations, and these specific combinations have been shown to induce thyroid cancer progression in mouse models." (PMID 38275415, 2024). "Recent studies have shown that inhibition of PI3K/Akt/mTOR signaling could be a promising molecular target for thyroid cancer therapy." (PMID 39166605, 2024). "Five hundred and sixty-seven miRNAs associated with nine autophagy proteins (ULK1, ATG16L1, MAP1LC3B, PRKAA1, ATG12, ATG 14, ATG5, mTOR and BECN1) were identified, of which sixty-two are accompanied by thyroid cancer, and only miR-125b is associated with the autophagy modulation in this pathology." (PMID 36980957, 2023). "The signaling of mTOR is activated in other types of clinically aggressive thyroid cancers." (PMID 36980552, 2023). "mTOR pathway targets are activated in thyroid cancer, and metformin may also inhibit the growth, migration and mesenchymal transition of thyroid cancer cell lines through the mTOR pathway other than the insulin pathway." (PMID 37773165, 2023). "Therapeutic approaches embracing the PI3K/AKT/mTOR pathway in differentiated thyroid cancer." (PMID 36980552, 2023). "TBK1 promoted tumor progression of thyroid cancer cells by activating the PI3K/Akt/mTOR pathway." (PMID 36988258, 2023). "The PPAR signaling pathway, the insulin signaling pathway, and the mTOR signaling pathway may be the critical pathways for controlling TNFRSF12A in thyroid cancer." (PMID 36142828, 2022). "However, AMPK activator/mTOR inhibitor can effectively inhibit various thyroid cancer cell lines growth." (PMID 36588732, 2022). "Interestingly, A GSEA indicated that WT1 is involved in the “MAPK signaling pathway” and “mTOR signaling pathway” in thyroid cancer patients." (PMID 35123502, 2022). "Therefore, examining mTOR pathway suppression by targeting GPX4 can provide further mechanistic insight into mTOR pathway signaling as a potential therapeutic target for advanced thyroid cancers." (PMID 36371529, 2022). "Similarly, the results of GSEA on TCGA data also showed that genes related to AKT/mTOR signaling were also enriched in thyroid cancer tissue compared with adjacent tissue." (PMID 35148777, 2022). "mTOR signaling might be highly activated in aggressive histological types of thyroid cancer and represents a promising target for therapy." (PMID 36106120, 2022). "Furthermore, ribosomal protein S6 kinase B1 (RPS6KB1) is a serine/threonine kinase in downstream of mTOR pathway, implicated in cell viability and inhibition of apoptosis through phosphorylating BAD protein in thyroid carcinoma." (PMID 36158686, 2022). "However, the upstream inducer and regulator of AKT/mTOR signaling pathway remain to be determined in thyroid cancer." (PMID 34512155, 2021). "Furthermore, as an important therapeutic target in various types of cancer, including thyroid cancer, mTOR exerts various impacts on multiple genes related to cell proliferation, among which 4E-BP3 is an important effector molecule." (PMID 34094961, 2021). "In addition, crosstalk between PI3K/AKT/mTOR signaling activation and multiple protumorigenic pathways has been well established in multiple cancer models, including thyroid cancers, and shown to play important roles in cancer initiation and progression." (PMID 34650915, 2021). "Importantly, PI3K/AKT/mTOR signaling activation is associated with reduced NIS expression and iodide uptake in thyroid cancer cells." (PMID 34650915, 2021). "In this study, we showed that MARCH6 MARCH6 would activate AKT/mTOR signaling pathway, which may contribute to thyroid cancer cell growth and migration." (PMID 34512155, 2021). "It has been reported that miR-17-5p could inhibited PTEN expression, therefore leading to suppression of the malignancy of thyroid cancer and inactivation of AKT/mTOR pathway, providing a novel avenue for treatment of thyroid cancer." (PMID 34130587, 2021).
thyroid cancer (continued). "Nevertheless, it is unclear whether the hypoxia-related mTOR/HIF1α pathway participates in thyroid carcinoma progression." (PMID 33968941, 2021). "Moreover, by the modulation of the Akt/mTOR pathway, mulberry anthocyanins (10 μg/mL) induced apoptosis and autophagy-dependent cell death in thyroid cancer cells (SW1736 and HTh-7)." (PMID 32927836, 2020). "Activation of the PI3K/AKT/mTOR pathway is a common feature in thyroid cancer." (PMID 31540307, 2019). "Furthermore, melanoregulin has been shown to regulate the invasion and proliferation of thyroid cancer cells via PI3K/AKT/mTOR pathway." (PMID 31223424, 2019). "The inhibition of mTOR promotes redifferentiation of thyroid cancer cells by upregulating NIS mRNA and protein expression, resulting in elevated iodine uptake through increased transcription at the level of thyroid transcription factor-1 (TTF1), which indicates TTF1 dependence for NIS expression." (PMID 31533238, 2019). "Alterations in the PI3K/AKT/mTOR cascade are well documented in thyroid cancer tumorigenesis." (PMID 31533238, 2019). "Because of the signaling convergence of both somatostatin receptor and mTOR pathway and the implication of both pathways in thyroid cancer, a therapeutic strategy of combined somatostatin analogue therapy and mTOR inhibition is likely to achieve improved efficacy." (PMID 30807575, 2019). "Furthermore, CDK8 and members of the mTOR pathway are correlated in a number of other cancers including thyroid carcinoma, thymoma, prostate adenocarcinoma, and liver hepatocellular carcinoma." (PMID 31628323, 2019). "The mammalian target of rapamycin (mTOR) pathway is overactivated in thyroid cancer (TC)." (PMID 29757257, 2018). "Thus, IMCA inhibits nuclear NR4A1-mediated mTOR pathways and represent a new class of mechanism-based drugs for thyroid carcinoma chemotherapy." (PMID 29498706, 2018). "However, further investigation is needed to understand the effects of mTOR inhibition on autophagy and apoptosis in thyroid cancer." (PMID 29262541, 2017). "Background. mTOR signaling would be a promising target for thyroid cancer therapy." (PMID 27274989, 2016). "It has been reported that mTOR signaling would be a promising target for thyroid cancer therapy." (PMID 27274989, 2016). "Combinations of vemurafenib and mTOR inhibitors should be further studied on human cancer xenografts on immunodeficient mice, to evaluate in vivo effects and potential clinical benefits for treatment of advanced thyroid cancer patients." (PMID 26284586, 2015). "Therefore, enhanced glycolysis may be the reason why mTOR/HIF1α/ENO1 promotes thyroid carcinoma progression." (PMID 33968941, 2021). "Therefore, we speculate that Akt/mTOR pathway inhibition induces both apoptosis and autophagy in human thyroid cancer cells following aloperine treatment." (PMID 31731481, 2019). "Some recent in vitro studies suggested that metformin may inhibit the growth of thyroid cancer cells through inhibition of the mammalian target of rapamycin (mTOR) pathway by activating the AMP-activated protein kinase (AMPK) or by diminishing the growth stimulation by insulin." (PMID 25303400, 2014). "These genetic alterations critically affect the clinical and pathological characteristics of thyroid cancer by activating the mitogen activated protein kinase (MAPK) and/or PI3K/AKT/mTOR signaling pathways." (PMID 39926346, 2025). "In contrast, thyroid cancer signalling, CXCR4, ILK, IL-8, IL-3, JAK/STAT and mTOR signalling pathways were significantly enriched in GWASLN6." (PMID 41520521, 2025).
thyroid cancer (continued). "Hyperactivation of the AKT/mTOR axis was observed in the majority of PTC samples we tested, and thyroid cancer cell lines along with cancer tissue specimens sustained a low basal autophagic activity." (PMID 39906716, 2025). "Further molecular mechanism studies revealed that SNHG3 knockdown upregulates key molecules in the AKT/mTOR and MAPK/ERK signaling pathways (p-AKT, p-mTOR, and p-ERK), thereby accelerating thyroid cancer progression." (PMID 41234719, 2025). "SQSTM1/p62 promotes thyroid cancer cell growth and induces autophagy by modulating the AKT/AMPK/mTOR signaling pathway." (PMID 38717641, 2024). "Metformin can inhibit thyroid cancer cell proliferation, migration, invasion and EMT by activating AMPK and subsequently inhibiting mTOR." (PMID 37773165, 2023). "In thyroid cancer, alternative splicing mediated by HNRNPF can contribute to conventional cancer-related pathways including RTK/RAS/MAPK and PI3K/AKT/MTOR signaling." (PMID 37968457, 2023). "Thyroid cancer (TC) cells employ multiple signaling pathways, such as PI3K/AKT/mTOR and RAS/Raf/MAPK, fostering cell proliferation, survival and metastasis." (PMID 37173925, 2023). "Metformin can inhibit insulin-induced growth stimulation in differentiated and undifferentiated thyroid cancer and thyroid cancer stem cells, and these effects of metformin are closely related to insulin/IGF signaling and AMPK/mTOR pathways." (PMID 37773165, 2023). "In this study, canagliflozin blocked glucose uptake, suppressed glycolysis and AKT/mTOR signaling activation, and increased AMPK activation in thyroid cancer cells." (PMID 37509506, 2023). "AKT/mTOR pathway and AMPK pathway have been proved to be related to thyroid cancer progress and cell energy metabolism." (PMID 35148777, 2022). "Taken together, canagliflozin inhibited AKT/mTOR pathway and promoted AMPK pathway activation in thyroid cancer cell." (PMID 35148777, 2022). "Here, we confirmed that canagliflozin inhibited the activation of AKT/mTOR pathway, and promoted AMPK signaling activation in thyroid cancer cell." (PMID 35148777, 2022). "Mechanistically, CREB3L1 overexpression can facilitate the dedifferentiation of papillary thyroid cancer cells into ATC cells, and promote thyroid cancer progression by regulating EMT process and the mTOR signaling pathway." (PMID 36171879, 2022). "The overexpressed Rab22a can activate the PI3K/AKT/mTOR signaling pathway, thereby promoting EMT of thyroid cancer cells and enhancing the proliferation, migration, and invasion of thyroid cancer cells." (PMID 35757470, 2022). "In thyroid cancer, the expression of Anp32e is upregulated and promotes the proliferation and migration of thyroid cancer cells by activating the AKT/mTOR/HK2 signaling pathway." (PMID 36263179, 2022). "Canagliflozin inhibited glucose uptake, glycolysis and AKT/mTOR signaling activation, and increased AMPK activation in thyroid cancer cell." (PMID 35148777, 2022). "Our data demonstrated that sodium selenite exhibits strong anticancer effects against thyroid cancer cells, which involved ROS-mediated inhibition of the AKT/mTOR pathway." (PMID 34094961, 2021). "In summary, MARCH6 significantly promotes thyroid cancer growth and migration by interacting with DHX9 and activating the AKT/mTOR pathway." (PMID 34512155, 2021). "As a classic oncogenic pathway in the development of thyroid cancer, the AKT/mTOR pathway is also closely related to metabolic stress and cellular nutritional status." (PMID 34094961, 2021). "MTOR inhibition promotes the expression of thyroid-specific genes and proteins and RAI uptake with TTF1-dependent redifferentiation in thyroid cancers." (PMID 33995657, 2021). "MREG is reported to suppress thyroid cancer cell invasion and proliferation through PI3K/Akt-mTOR signaling pathway." (PMID 34178023, 2021). "Overall, MARCH6 functions as a potential oncogene in thyroid cancer by destabilizing DHX9 and activating AKT/mTOR signaling." (PMID 34512155, 2021).
thyroid cancer (continued). "An mTOR signaling repressor gene, EIF4EBP3, was found to be involved in the anticancer effect of selenite in thyroid cancer." (PMID 34094961, 2021). "Given the known negative regulatory effect of AMPK on mTOR protein, it is conceivable that circ_0008274 activates mTOR pathway via inhibiting AMPK protein, leading to thyroid cancer development and progression." (PMID 33158279, 2020). "A recent study found that ROS levels in thyroid cancer cells decreased after 24 h of treatment with 20–50 μM NaHS, which activated the PI3K/AKT/mTOR signalling pathway to promote tumour cell proliferation and migration." (PMID 31949127, 2020). "Most of the recently discovered targeted therapies inhibit the known oncogenic mechanisms in thyroid cancer initiation and progression such as MAPK pathway, PI3K/Akt-mTOR pathways, or VEGF." (PMID 32528402, 2020). "To further verify the downstream molecular mechanism of the miR-96-3p/SDHB in metastasis in thyroid cancer, we focused on the AKT/mTOR pathway, which has been proved to be cellular biological function of the cancer." (PMID 31749660, 2019). "Our results demonstrated that 25–50 μM NaHS promoted the proliferation, viability, migration, and invasion of human thyroid carcinoma cells by downregulating ROS levels and upregulating phosphorylations of PI3K, AKT, and mTOR." (PMID 31223424, 2019). "After treatment with 25-50 μM NaHS, the ROS levels were decreased and the protein levels of p-PI3K, p-AKT, p-mTOR, H-RAS, p-RAF, p-MEK1/2, and p-ERK1/2 were increased, whereas 200 μM NaHS exerted opposite effects in human thyroid carcinoma cells." (PMID 31223424, 2019). "We focused on the effect of IMCA on thyroid cancer cell viability, apoptosis, nuclear export of NR4A1, and cell proliferation regulated by the mTOR pathway." (PMID 29498706, 2018). "Of interest, Src is upstream of the AKT/mTOR and MAPK pathways, both which have been shown to be important pathways for thyroid cancer progression." (PMID 29262541, 2017). "Another study reported reactive oxygen species (ROS) accumulation and interrupted RAS/RAF/ERK and PI3K/mTOR signaling pathways to be connected with apoptotic events in Bel-sensitive WRO82–1 and 8505C thyroid carcinoma cells." (PMID 27468826, 2016). "In thyroid carcinomas, inhibition of PI3K or mTOR enhances iodine uptake, raising the possibility of enhanced sensitivity to 131I therapy in cancers in which this pathway is activated." (PMID 26793165, 2015). "Concomitant use of a RAF inhibitor, RAF265, and a dual PI3K/mTOR inhibitor, BEZ-235, was another effective combinatorial therapy against thyroid cancer in xenograft mouse models." (PMID 23509459, 2013). "We assessed the utility of the dual PI3K/mTOR inhibitor NVP-BEZ235 (BEZ235) as single agent therapy and in combination with conventional chemotherapy for thyroid cancer." (PMID 23077520, 2012). "Our data suggest that ATC relies on PI3K/mTOR activity, and interruption of this pathway with BEZ235 impairs ATC growth more significantly than other thyroid cancer histologies." (PMID 23077520, 2012). "This dual suppression aligns with the therapeutic strategy of targeting both PI3K/AKT/mTOR and MAPK/ERK pathways, which are often co-activated in thyroid cancers — especially in aggressive subtypes — and contribute to tumor survival, proliferation, and therapeutic resistance." (PMID 41477125, 2025). "In osteosarcoma and bladder cancer, SNHG3 acts as an oncogenic factor; whereas in thyroid cancer, SNHG3 may function as a tumor suppressor gene by negatively regulating the AKT/mTOR and MAPK/ERK signaling pathways." (PMID 41234719, 2025). "The inhibition of Apatinib-induced autophagy with CQ in vitro increased apoptosis in thyroid cancer KHM-5M and C643 cells through the downregulation of p-Akt and p-mTOR, while Apatinib/CQ therapy augmented the suppression of the mice thyroid cancer xenograft in vivo." (PMID 38256019, 2024).
thyroid cancer (continued). "Importantly, ANP32E stimulates the AKT/mTOR/HK2 signaling pathway to accelerate cell proliferation, migration and glycolysis in thyroid carcinoma." (PMID 38585643, 2024). "Similarly, in lung cancer, the overexpression of ANXA8 activates the EGFR/AKT/mTOR signalling pathway to promote proliferation, while in thyroid cancer, increased ANXA1 promotes thyroid cancer proliferation by mediating IL-6/JAK2/STAT3." (PMID 36936694, 2023). "Furthermore, miR‐133a‐3p can regulate the PI3K/AKT/mTOR signaling pathway in thyroid cancer by modulating ZEB1‐AS1 and targeting LPAR3 and EGFR, inhibiting thyroid cancer cell proliferation while promoting cell death." (PMID 36305754, 2023). "In addition, TAM-induced IGF promotes thyroid cancer stemness and metastasis by activating the PI3K/AKT/mTOR pathway, and TGF-β induces M2-like macrophage polarization." (PMID 36838713, 2023). "Taken together, these results suggested that, in thyroid cancer cells, Rab22a may promote EMT through upregulating PI3K/AKT/mTOR signaling pathway." (PMID 35757470, 2022). "Then we investigated whether AKT/mTOR pathway and AMPK pathway were involved in the effects of canagliflozin on thyroid cancer growth." (PMID 35148777, 2022). "Moreover, the malignant phenotypes induced by AURKA overexpression were partly blocked by AKT inhibitors and mTOR inhibitors, indicating that the oncogenic role of AURKA in thyroid cancer cells partly depends on the PI3K/AKT signalling pathway." (PMID 36471438, 2022). "PI3K/AKT/mTOR signaling activation, which is negatively regulated by the tumor suppressor gene PTEN, enhances cell proliferation and migration in multiple cancer cells, including thyroid cancer cells." (PMID 34650915, 2021). "Similarly, in thyroid cancer cells, 200 μM NaHS treatment inhibits migration activities by deactivating the PI3K/AKT/mTOR and MAPK pathways." (PMID 33390834, 2021). "Besides, treatment of thyroid cancer cells with 25-50 μM NaHS effectively enhances migration and invasion by activating PI3K/AKT/mTOR and MAPK pathways." (PMID 33390834, 2021). "The AKT/mTOR and MAPK pathways are major pathways in the development of thyroid cancer." (PMID 34094961, 2021). "Therefore, in this study, we aimed to explore the role of abnormal TSH-TSHR signaling activation in regulating iodide uptake and cell mobility in thyroid cancer and its relationship with PI3K/AKT/mTOR signaling." (PMID 34650915, 2021). "Potential therapies in advanced thyroid cancer patients may combine vemurafenib with inhibitors of CRAF, HER2/HER3, ERK, and/or mTOR to delay or abort development of resistance." (PMID 26735176, 2016). "In this study we investigated the combination of vemurafenib and mTOR inhibitors, metformin and rapamycin, which has not yet been explored in thyroid cancer." (PMID 26284586, 2015). "Interestingly, AMPK suppressed the phosphorylation of ERK (extracellular-signal-regulated kinase) and p70S6K (mTOR target), in BRAF V600E mutant thyroid cancer cells, but rather increased their phosphorylation in wild-type cells." (PMID 27919039, 2014). "In thyroid cancer, genetic alterations affecting the PI3K/mTOR pathway have been identified." (PMID 23077520, 2012). "Similarly, in combination of mTOR and MEK inhibitors also demonstrated therapeutic advantage in treating thyroid cancer, providing further evidence that targeting both PI3K/mTOR and MAPK pathways is a potential therapeutic strategy for this disease." (PMID 23077520, 2012). "However, none of these studies examined bavachinin in thyroid carcinoma or demonstrated its dual inhibition of the PI3K/AKT/mTOR and MAPK/ERK pathways, highlighting the novelty of our findings." (PMID 41477125, 2025). "However, the relationship between Rab22a and the PI3K/AKT/mTOR signaling pathway in thyroid cancer has never been explored." (PMID 35757470, 2022).